TET1 (tet methylcytosine dioxygenase 1)
Diseases named in the same sentence as TET1 in open-access papers (continued):
Sharing a sentence is not in itself a finding about the gene and the disease.
breast cancer (continued). "The current results suggest TET-1 as responsible for the IL-1β-dependent tumor progression of the MCF-7 cell line, indicating its potential therapeutic treatment as a druggable target in breast cancer acting on progression and bone metastasis." (PMID 36499741, 2022). "While plenty of evidence has shown that TET1 is a tumor suppressor gene, not less evidence has proved that TET1 supports oncogenic changes in breast cancer, especially after the discovery of the short isoform of TET1." (PMID 35646706, 2022). "Our research demonstrates that TET1 is expressed at low levels in breast cancer, leading to the low demethylation of ADCY6, inhibiting ADCY6 protein expression, and regulating the malignant biological behaviour of breast cancer through EMT signalling pathway." (PMID 35978806, 2022). "Moreover, FECR1 [a circular RNA of Friend leukemia virus integration 1 (FLI1)], was shown to recruit TET1 to the promoter of FLI1 oncogene, which leads to promoter hypomethylation and FLI1 oncogene overexpression in breast cancer cells." (PMID 35646706, 2022). "In the current study our results indicate that the picture seems to be more complicated and that the role of TET1 in breast cancer is not black and white." (PMID 35646706, 2022). "In breast cancer, FOXA1 which activates TET1 gene expression could also recruit TET1 to a subgroup of enhancer regions." (PMID 34885145, 2021). "One study reported that in basal-like breast cancer (BLBC), the activation of nuclear factor кB (NF-кB) could suppress TET1 by binding to its promoter, highlighting a novel epigenetic-immunity connection." (PMID 34957093, 2021). "TET1 positively modulated HOXA9 by directly binding to or inducing the histone binding of H3K4Me3 to the HOXA gene promoter regions, leading to local demethylation and gene transcription in breast cancer." (PMID 34957093, 2021). "As the hypoxia-mediated deregulation of TET methylcytosine dioxygenase 1 (TET1) and TET3 has been shown to promote breast cancer TIC properties, such hypoxia-induced alterations of epigenetic controls can be considered as an important driving force of malignant tumor progression." (PMID 31159361, 2019). "Both TET1 and HOXA9 suppressed breast cancer development in nude mice." (PMID 28780773, 2017). "The idea that TET1 is itself epigenetically regulated and that its activation regulates a network of genes has been supported in a breast cancer cell line by experiments manipulating expression of HMGA2 (high mobility group at-hook 2), which is an upstream repressor of TET1 expression." (PMID 28587163, 2017). "This further supports the ideas that miR-29b influence BC metastasis mainly through targeting TET1 and that TET1 plays a crucial role in EMT regulation, which explains the observation that low levels of miR-29b in BC patients promotes breast cancer development." (PMID 29254230, 2017). "Low levels of TET1, TIMP2, and TIMP3 correlate with advanced stage in breast cancer patients." (PMID 26861406, 2016). "Moreover, TET1 promoter was methylated in high-mobility group AT-hook 2 (HMGA2; chromatin remodeling factor)-depleted breast cancer cells." (PMID 25557833, 2015). "Subsequent to TET1 gene expression, TET1 auto-demethylates its promoter and, subsequently, the demethylation of the promoter of homeobox A (HOXA) genes, HOXA7 and HOXA9, culminating in the effect from the TET1, HOXA7, and HOXA9 genes suppressing breast cancer invasion and metastasis." (PMID 38994941, 2024). "Finally, we experimentally (i) confirmed the effect of FOXA1 expression on DNA methylation patterns at regions bound by FOXA1 in the MCF-7 breast cancer cell line, and (ii) detected interactions of FOXA1 with TET1 and TET2 proteins both in an in vitro setup and at endogenous levels." (PMID 35440061, 2022). "However, the effect of different hormone treatment on different TET1 isoforms in breast cancer was not tested." (PMID 35646706, 2022).
breast cancer (continued). "In addition, TET1 mediated demethylation on CpG island increases the expression of endogenous LRIG1 in basal/triple negative breast cancer cells, and changes the malignant biological behavior in breast cancer cells through epigenetic mechanisms." (PMID 35978806, 2022). "Increasing the expression of TET1 could inhibit the malignant biological behaviour of breast cancer cells and suggests that the high methylation level of ADCY6 is due to the low TET1 expression in breast cancer." (PMID 35978806, 2022). "However, in another study, hypoxia could conversely increase the expression of TET1, TET3 as well as 5hmC level in promoters, leading to carcinogenesis and poor prognosis of breast cancer patients via a TET-TNFα-p38-MAPK signaling." (PMID 34957093, 2021). "While overexpressing TET1 using viral vectors in patients might not be clinically feasible, this discovery suggests that restoring normal 5hmC content may have therapeutic potential for breast cancer." (PMID 29593282, 2018). "In basal-like breast cancer (BLBC), overall TET1 expression is elevated compared to normal tissue, and is negatively correlated with levels of immune defense markers and cells." (PMID 40014756, 2025). "However, we do not observe FOXA1 binding sites around the TET1 locus and TET1 is not expressed in HCC1954 breast cancer cells nor in TCGA BRCA samples and other TETs have very low levels of expression." (PMID 35331302, 2022). "However, Cox regression analysis did not indicate TET1, 2, 3 and TDG mRNAs were independent predictors of breast cancer." (PMID 26207381, 2015).
acute myeloid leukemia (41 papers, 2012 to 2025). Acute myeloid leukemia (AML) is a group of neoplasms arising from precursor cells committed to the myeloid cell-line differentiation. "Especially in acute myeloid leukemia, translocation and mutations of TET1 and TET2 gene are frequently observed." (PMID 26833217, 2016). "High TET1 expression has been associated with poor outcomes in acute myeloid leukemia." (PMID 40520993, 2025). "TET1 was identified as a fusion partner of the mixed-lineage leukemia (MLL) gene from the breakpoint of chromosomal translocation in acute myeloid leukemia (AML), and loss of TET2 is strongly associated with myelodysplastic syndromes, myeloproliferative neoplasms, and myeloid leukemias." (PMID 33921666, 2021). "The TET1 gene was initially discovered as a gene linked to acute myeloid leukemia (AML) that forms a fusion protein the histone H3 Lys 4 (H3K4) methyltransferase mixed-lineage leukemia (MLL)." (PMID 32466098, 2020). "Homoharringtonine, approved for chronic myeloid leukemia, inhibits acute myeloid leukemia growth by targeting the specificity protein 1 (SP1)/TET1 axis and reducing 5hmC levels." (PMID 40520993, 2025). "Although TET1-MLL translocation was observed in acute myeloid leukemia (AML) as early as 2003, the exact biochemical activity of TET proteins and their functional roles have been extensively studied since 2009." (PMID 34885145, 2021). "High expression of TET1 indicates a poor prognosis in cytogenetically normal acute myeloid leukemia and promotes cisplatin-resistance in ovarian cancer." (PMID 32127798, 2020). "TET1 is known as a tumor suppressor protein although it presents carcinogenic activity in acute myeloid leukemia and gastric carcinoma." (PMID 30551127, 2018). "TET1 was reported to fuse with the MLL gene to produce a chimeric transcript in acute myeloid leukemia (AML)." (PMID 28769976, 2017). "TET1 was first identified as a fusion partner of the mixed lineage leukemia (MLL) gene in acute myeloid leukemia, and it is now clear that TET1 plays an essential oncogenic role in MLL-rearranged leukemia." (PMID 26973719, 2016). "Meanwhile, Tet1 has been identified as a fusion partner of the MLL gene in acute myeloid leukemia and also involves in some kinds of leukemia." (PMID 27449105, 2016). "In 2016, Jiang et al43 demonstrated that in acute myeloid leukemia, miR-22 was suppressed through epigenetic repression involving TET1, along with SIN3 transcription regulator family member A (SIN3A), EZH2, and growth factor independent 1 (GFI1), as well as DNA copy-number loss." (PMID 40520993, 2025). "However, TET1 expression was reported to be upregulated in acute myeloid leukemia, suggesting an opposite role of TET1 and TET2 during leukemogenesis." (PMID 38403247, 2024). "However, clinical studies have revealed that TET1 is highly expressed in some cases of the hematological malignancies including acute myeloid leukemia." (PMID 33705482, 2021). "For instance, TET1 has been considered as a critical oncogenic epigenetic regulator in acute myeloid leukemia (AML), which plays its role by promoting the expression of oncogenic targets, including HOXA9, MEIS1 and PBX3, and suppressing the expression of tumor suppressor miR-22." (PMID 34957093, 2021). "In humans with acute myeloid leukemia (AML), the MLL gene on 11q23 is fused to the LCX leukemia-associated protein with a CXXC domain gene on 10q22, which was cloned as Ten-eleven translocation methylcytosine dioxygenase 1 (TET1)." (PMID 30574144, 2018). "In addition, increased TET1 expression was associated with the poor survival of patients with cytogenetically normal acute myeloid leukemia (CN-AML), suggesting that TET1 may play a role as an oncogene in AML." (PMID 36675240, 2023). "The first member of TET family, TET1, was discovered in acute myeloid leukemia (AML) cells as a fusion partner for histone H3 Lys4 methyltransferase." (PMID 37239005, 2023).
acute myeloid leukemia (continued). "The Ten Eleven Translocation 1 (TET1) gene, which was originally identified as a fusion partner of Mixed Lineage Leukemia (MLL) in acute myeloid leukemia (AML), encodes an epigenetic modifying molecule." (PMID 33705482, 2021). "Our findings are consistent with recent reports that TET1 acts as an oncogene in acute myeloid leukemia (AML) development and that high TET1 levels are predictive of poor overall survival in AML." (PMID 31266538, 2019). "TET1 was firstly identified as a fusion partner of mixed lineage leukemia (MLL) in acute myeloid leukemia (AML), and the downregulation of Tet1 has been shown to promote cancer invasion and metastasis." (PMID 29156803, 2017). "Subsequent research found that TET1 is a fusion partner of mixed-lineage leukemia (MLL)-rearranged acute myeloid leukemia (AML)." (PMID 28488246, 2017). "Zhang et al51 found a significant reduction in TET1 expression alongside elevated TET2 and TET3 levels, suggesting a complex role of TET enzymes in acute myeloid leukemia pathogenesis." (PMID 40520993, 2025). "was to assess the role of C-KIT, TET1 and TET2 expression in the diagnosis and prognosis of acute myeloblastic leukemia (AML)." (PMID 36371552, 2023). "Wang et al48 linked TET1 expression to M0/M1 morphology and nucleophosmin 1 (NPM1) mutations, correlating with worse survival rates, particularly in acute myeloid leukemia without CCAAT enhancer binding protein alpha (CEBPA) mutations." (PMID 40520993, 2025). "In 2002, a genetic alteration in the TET1 gene was identified through the detection of a chromosomal rearrangement, specifically the translocation 10q22-11q23 of TET1 and Lysine Methyltransferase 2A (MLL1) genes in acute myeloid leukemias." (PMID 38203443, 2023).
leukemia (41 papers, 2013 to 2025). A malignant (clonal) hematologic disorder, involving hematopoietic stem cells and characterized by the presence of primitive or atypical myeloid or lymphoid cells in the bone marrow and the blood. "This is further supported by evidence that TET2-deficient leukemia cells rely on residual TET activity coming from TET1 and TET3 for their proliferative advantage and survival." (PMID 35085104, 2022). "In cancer, the global loss of 5hmC has been frequently associated with TET2 somatic mutations in leukemia or with TET1 silencing in solid tumors." (PMID 27587280, 2016). "Overexpression of DNMT1 and DNMT3a, coupled with suppression of MS and TET1, may drive the aberrant epigenetic modifications associated with leukemia development." (PMID 41254398, 2025). "Concurrently, Jamalpour et al45 reported a network involving SH2 domain-containing adaptor protein B (SHB), B-cell lymphoma 6 corepressor like 1 (BCORL1), and TET1 that enhances lymphoid traits, vascular development, and leukemia cell survival." (PMID 40520993, 2025). "TET proteins were named “ten‐eleven translocations” after the discovery of TET1 in a chromosomal translocation process that fused the mixed lineage leukemia gene on chromosome 11 with the TET1 located on chromosome 10." (PMID 40599235, 2025). "For example, hsa_circ_0121582 was found to inhibit leukemia cell proliferation by recruiting DNA demethylase TET1 to the promoter region of GSK3β." (PMID 37124518, 2023). "TET1 was first identified as one of the MLL fusion partners in leukemias; it showed the highest expression levels in embryonic stem cells and in early embryogenesis." (PMID 32089682, 2020). "Later, TET1 was verified to promote cell proliferation and induce leukemia by activating the Hoxa9/Meis1/Pbx3 signaling pathway." (PMID 32014008, 2020). "TET2 loss-of-function mutations were identified in myeloid and lymphoid hematological malignancies, whereas the TET1 overexpression found in mixed lineage leukemia (MLL)-rearranged leukemia is oncogenic." (PMID 28032215, 2017). "Both TET1 and TET2 are implicated in cancer: TET1 is an MLL partner in cases of acute myeloid and lymphoid leukemias and has been reported to function as an oncogene in MLL-rearranged leukemias as well as a tumor suppressor in other contexts [reviewed in Ref." (PMID 28408905, 2017). "Contrasting with these reports, there is experimental evidence that TET1 acts as an oncogene in MLL-rearranged leukaemia and breast tumour malignancies." (PMID 28228863, 2017). "While loss of TET1 and TET2 expression is associated with solid cancers, implying a tumor suppressor role, TET1 exhibits a clear oncogenic role in the context of genomic rearrangements such as in MLL-fusion rearranged leukemia." (PMID 26869355, 2016). "TET1 catalytic activity plays an indispensable oncogenic role through coordination with MLL-fusion proteins in MLL-rearranged leukemia." (PMID 27557497, 2016). "Recent report indicated that TET1 is significantly up-regulated in MLL-rearranged leukemia and is a direct target gene of MLL-fusion proteins." (PMID 26869355, 2016). "Additionally, circ_0121582 exerted a repressive effect on leukemia growth by promotion of GSK3β expression through sponging miR-224 and direct binding to ten-eleven translocation 1 (TET1)." (PMID 37124518, 2023). "Incidentally, fusions of MLL with TET1 were reported in leukemia patients." (PMID 36056023, 2022). "Oncogenic TET1 plays an important role in the development of MLL-rearranged leukemia." (PMID 31266538, 2019). "TET1, a RNA m5C demethylase, acts as a tumor suppressor in leukemia." (PMID 30062093, 2018). "TET1 is differentially expressed in many cancers, including leukemia." (PMID 29100411, 2017). "Furthermore, Huang and co-workers have found that TET1 expression is promoted via MLL-fusion proteins directly binding to the promoter region of TET1 in MLL-rearranged leukemia." (PMID 27557497, 2016).
leukemia (continued). "Thus, our study uncovers a novel epigenetic regulation mechanism in leukaemia involving the cooperation between TET1/GFI1 and polycomb factors." (PMID 27116251, 2016). "Interestingly, while TET genes are frequently downregulated in tumors, a recent study reported that TET1 is upregulated in MLL-rearranged leukemia which is accompanied by a global increase in 5hmC levels, suggesting a role for TET1 as an oncogene instead of a tumor suppressor." (PMID 24172544, 2013). "Some pluripotency genes were also identified, as well as cancer genes, such as TET1, ALK, EP300, ERG, MKL1 and PHF6, already described as being involved in leukemia." (PMID 37174060, 2023). "For TET1, overexpression has been reported in both MLL-rearranged leukemia and cytogenetically normal AML patients and was found to be correlated with a poor OS in the latter group, thus suggesting a pro-oncogenic role for TET1 in hematological cancers." (PMID 36059621, 2022). "Homoharringtonine exerts antitumor effects by inhibiting the synthesis of target proteins, such as phospho-eIF4E, SP1/TET1/5hmC, Smad3, and TGF-β pathway components, and NF-κB repressing factor, and promotes apoptosis in leukemia cells." (PMID 35873796, 2022). "As chromosomal translocation partners, TET family members, including TET1 and TET2, were initially found in leukemia and proven to be key regulators of DNA demethylation owing to their dioxygenase activity." (PMID 35235761, 2022). "To assess the role of these enzymes in the methylation of CAT promoter in leukemia cells, first we characterized DNMT1, DNMT3A, TET1-3 mRNA expression levels in CLL and HD B cells." (PMID 36112236, 2022). "TET1 is a direct target of the MLL-fusion protein and is significantly upregulated in MLL-rearranged leukemia, leading to a global increase 5hmC, thus playing an oncogenic role." (PMID 27446199, 2016). "TET1 was first identified as a fusion partner of the mixed lineage leukemia (MLL) gene in adult and pediatric leukemias with the translocation t(10:11)(q22;q23)." (PMID 24202321, 2013). "To test our hypothesis, we performed qRT-PCR to quantify the effect of both drugs on the transcription of the three isoforms, TET1, TET2, and TET3, in U937 leukemia cells." (PMID 41516186, 2025). "The function of MLL-TET1 fusion protein is still unknown, but it was showed that TET1 is involved in MLL-rearranged leukemia." (PMID 27446199, 2016). "Recently, it was reported that the gene encoding TET2 but not TET1 and TET3 was frequently mutated, and it was identified as the relevant tumor suppressor gene, which is mutated in leukemia." (PMID 26366235, 2015). "The ten-eleven-translocation 1 (TET1) enzyme was identified first as an MLL fusion partner in leukemia, but its biological function was not known until 2009, when it was identified as a dioxygenase capable of converting 5-mC to 5-hmC." (PMID 24202321, 2013). "Since TET1-NBs have never been described, we were intrigued to identify whether these nuclear hotspots interact with the most commonly studied nuclear structures, such as Promyelocytic Leukemia nuclear bodies (PML-NBs) and/or Cajal bodies (CB)." (PMID 38583183, 2024). "In Haferlach leukemia samples, overexpression of TET1 and TET2 was identified, whereas TET3 downregulation was noted in Andersson leukemia samples." (PMID 39519332, 2024).